BRCA1 (BRCA1 DNA repair associated)
Diseases named in the same sentence as BRCA1 in open-access papers (continued):
Sharing a sentence is not in itself a finding about the gene and the disease.
breast cancer (continued). "Women with BRCA1 or BRCA2 mutations are at an increased risk for breast cancer at a young age, and this risk is speculated to rise even higher due to hormonal changes during pregnancy." (PMID 31661803, 2019). "In unselected patients, BRCA1 and BRCA2 mutations are reported in ranges of 0.3%–13% and 0.75–7.41%, respectively, while in high-risk/hereditary/familiar breast cancer patients, mutations in BRCA1 and BRCA2 were reported in 0.9%–16.6% and 0.49%–18.2%, respectively." (PMID 30792813, 2019). "Our model shows potential for improved risk counseling, but decision-making regarding contralateral preventive mastectomy, especially in the general breast cancer population where limited information of the mutation status in BRCA1/2 is available, remains challenging." (PMID 31847907, 2019). "However, for men who inherit a PV in a high-risk breast cancer gene, the risk of breast cancer is substantially elevated, with lifetime estimates of 4% for BRCA1 PVs and 7% for BRCA2 PVs." (PMID 30832243, 2019). "We detected 17 BRCA1/2 variants in 18 of 216 (8.3%) index patients with high‐risk breast cancer." (PMID 30968603, 2019). "Highly penetrant mutations in BRCA1 gene constitute high risk of breast cancer." (PMID 31759379, 2019). "However, despite this potential underestimation, the study found an association with better breast cancer-specific survival for BRCA1 mutation carriers after BRRM." (PMID 31302855, 2019). "Breast cancer was the most commonly diagnosed cancer in this cohort of women; however, most of these women were not at increased risk given that all the particpants had been tested for a BRCA1 mutation and those with a mutation were excluded." (PMID 31890061, 2019). "On the one hand, mutation of BRCA1 leads to breast cancer formation." (PMID 31697643, 2019). "In addition, studies have reported an increased risk of male breast cancer associated with germline mutations in BRCA1, although it represents a lesse frequent association than that with BRCA2 germline mutations." (PMID 31244284, 2019). "Evidence that supports the role of hormone signaling in the genesis of BRCA1-mutated breast cancers includes studies demonstrating that bilateral prophylactic oophorectomy reduces the risk of mammary tumors in mice, with a mammary targeted deletion of BRCA1." (PMID 31771627, 2019). "Therefore, the contribution of BRCA1 gene mutations to breast cancer in Bangladeshi population remains relatively unexplored." (PMID 31759379, 2019). "In addition, the PARP inhibitor olaparib has limited effects on breast cancer patients harboring germline mutations of BRCA1, especially the mutant with increased expression of BRCA1 exon 11 skipping (BRCA1-Δ11q)." (PMID 31065692, 2019). "Inherited mutations in the BRCA1 gene are responsible for the major hereditary breast cancer cases." (PMID 30806067, 2019). "Similarly, these features were found to be enriched in BRCA1-deficient breast cancers from WSI and TCGA." (PMID 31022191, 2019). "Our data suggest that BRCA1/2 variants may contribute to the pathogenesis of familial breast cancer in Bahrain." (PMID 31131559, 2019). "On the other hand, adequate levels can lower the risk of breast cancer in BRCA1 gene carriers." (PMID 31505792, 2019). "As expected, among the group with sporadic breast cancer, the second most common subtype was luminal A. Moreover, a substantial number (30%) of tumors from Group 1 were classified as basal-like (88.8% of them with a germline mutation in BRCA1)." (PMID 31244284, 2019). "This may be particularly relevant to the TNBC subtype of breast cancer, which shares similar molecular features to the tumors arising from BRCA1/FANCS and BRCA2/FANCD1-associated DNA repair deregulation." (PMID 30789902, 2019).
breast cancer (continued). "Despite the fact that each modifier explains a small proportion of genetic variation of breast cancer development in carriers of BRCA1 pathogenic variants, still a large proportion of risk variation is unknown." (PMID 31395037, 2019). "Clinical studies have shown that prophylactic bilateral mammectomy or bilateral oophorectomy can reduce 50%–90% of the risk of breast and ovarian cancer in women who have family history of breast cancer and carry BRCA1/2 mutations (Domchek & Kaunitz, 2016; Rizvi, Truong, & Truong, 2017)." (PMID 30968603, 2019). "Because of modifiers (including genetic background and environmental factors), the characteristics of breast cancer harboring a BRCA1/2 mutation in the Japanese population might be different from that of other races." (PMID 31143373, 2019). "Breast cancers occurred in most germline BRCA1 mutation carriers are TNBC." (PMID 30828495, 2019). "Over half of the women (55%, 64/117) correctly interpreted that their negative-screen result indicated it was unlikely that they carried a BRCA1/2 mutation, but fewer women (38%, 44/116) correctly understood that they remained at average risk for breast cancer." (PMID 31270367, 2019). "Our findings show that BRCA1/2 mutations account for one in four cases of hereditary breast/ovarian cancer, one in five cases of male breast cancer, and one in eight cases of early-onset breast cancer in Pakistan." (PMID 31528241, 2019). "However, most women (87%) incorrectly agreed “that about half of all breast cancers are caused by mutations in BRCA1 and BRCA2”." (PMID 31270367, 2019). "Finally, it has also been found that RANKL and RANK are highly expressed in pre-malignant lesions, as well as in breast cancer samples from both BRCA1 and BRCA2 human mutation carriers." (PMID 30621730, 2019). "Interestingly, this level of screening uptake was higher than other reported levels in female carriers of pathogenic variants in BRCA1/2, another population of women at high-risk of developing breast cancer." (PMID 31121919, 2019). "SNP18 has little predictive value as would be expected, as the majority of individual SNPs are associated with ER+ tumours, with only three predicting ER− cancer risk which are also predictive for breast cancer in women with BRCA1 pathogenic variants, where the cancers are predominantly ER−." (PMID 30941651, 2019). "Interestingly, both BRCA1 promoter hypermethylated tumors and BRCA1 mutated tumors share similar characteristics such as low pRb expression and being associated with basal/triple-negative subtype of breast cancer." (PMID 31023256, 2019). "Deficiency in BRCA1 gene is considered in high risk family with breast cancer." (PMID 30806067, 2019). "Interestingly, an association of the SNP309GG genotype with an earlier onset was also observed in several studies of familial breast cancer, particularly in BRCA1 mutation carriers." (PMID 30691044, 2019). "For instance, as of May 2018, Breast Cancer Information Core database contains information on relative clinically relevant variants across BRCA1 and BRCA2 genes, implicated in hereditary breast cancer development, based on the 11 344 affected population size." (PMID 31511888, 2019). "BRCA1-associated breast cancer originates from luminal progenitor cells." (PMID 30995943, 2019). "In conclusion, this is the first report on the breast cancer predisposition factors in the population of Bahrain and our data suggest that BRCA1 and BRCA2 variants may contribute to the pathogenesis of familial breast cancer in Bahraini patients." (PMID 31131559, 2019). "There also is breast cancer risk reduction from RRSO in BRCA1 patients but to a lesser degree." (PMID 31342359, 2019). "In addition to the loci summarized above, a GWAS approach identified the 19p13 chromosomal region as a modifier of breast cancer risk in BRCA1 mutation positive individuals." (PMID 31379942, 2019). "BRCA1/2 pathogenic variants were found in 1.8% of unselected breast cancer patients." (PMID 30175445, 2019).
breast cancer (continued). "However, little is still known about the relationship between the BRCA1 mutation, the incidence of breast cancer and oral homeostasis." (PMID 31597313, 2019). "Several characteristics associated with an increased likelihood of a pathogenic BRCA1 or BRCA2 variant include young age of breast cancer onset (<45 years), epithelial ovarian cancer, triple negative breast cancer, or multiple relatives with breast and/or ovarian cancer." (PMID 31531966, 2019). "However, the scenario where BRCA1/2 and other high/moderate risk genes for breast cancer are tested shows a positive rate of 20.2% with a relative low VUS rate (16.2%)." (PMID 31159747, 2019). "These myoepithelial perturbations in normal breast tissues of BRCA1 germline mutation carriers may play a role in their higher risk of breast cancer." (PMID 31519911, 2019). "We therefore investigated whether S63845 could enhance the efficacy of the clinical PARP inhibitor (PARPi) olaparib, which is currently used for treatment of BRCA1-mutated breast cancer patients." (PMID 30674894, 2019). "Recent studies have found that BRCA1/2, a breast cancer susceptibility gene, is closely related to triple-negative breast cancer (TNBC) and can repair DNA damage through homologous recombination, and its mutation can be used to predict the efficacy of PTX in TNBC chemotherapy." (PMID 31101119, 2019). "Breast cancer patients with hereditary BRCA1 mutations usually develop basal-like tumors." (PMID 31013830, 2019). "Furthermore, the BRCA1 gene is also crucial in breast cancer, which has an impact on breast cancer risk." (PMID 31213036, 2019). "Among basal-like breast cancers, 10-25% are associated with a germline BRCA1 mutation." (PMID 31225507, 2019). "Furthermore, authors identified six single-nucleotide polymorphisms in the locus encoding for human RANK (TNFRSF11A), that are significantly associated with breast cancer risk in a wide series of BRCA1 mutation carriers." (PMID 30621730, 2019). "In a large, clinically representative breast cancer cohort, we examined the prevalence and characteristics of BRCA1/2 germline mutation carriers and compared our results with BRCA mutation carriers already identified through a national clinical BRCA screening program." (PMID 30175445, 2019). "Conversely, over 80% of breast cancer patients with a BRCA1 mutation have TNBC." (PMID 30934991, 2019). "In addition, one mutation in additional 957 BRCA1/2 uninformative breast cancer families was found through the mutation hotspot screening." (PMID 30967997, 2019). "The number of TILs significantly increased in BRCA1-mutated breast cancer tumors than the wild-type ones, suggesting that loss of BRCA1 function might elicit tumor inflammation." (PMID 31023256, 2019). "In conclusion, BRCA1/2 mutation prevalence in unselected breast cancer patients was 1.8%." (PMID 30175445, 2019). "These cells are hypothesized to be the foundation for the formation of basal-like breast cancers that are frequently observed in women with a BRCA1 mutation." (PMID 31069010, 2019). "It has previously been shown in breast cancer that HR deficiency caused by BRCA1 inactivation is accompanied by an increase of tumor infiltration with CD4-positive T cells, CD8-positive cytotoxic T cells, PD-L1 expression, and possibly response to immune checkpoint inhibition." (PMID 31549213, 2019). "Breast cancer patients carrying germline BRCA1 or BRCA2 mutations represents around 5% of cases." (PMID 31336685, 2019). "We also observed that patients in BRCA mutation group had significantly higher personal history and family history of breast cancers reflecting the fact that mutations in the BRCA1/2 genes is the most common cause of hereditary forms of both breast and ovarian cancer." (PMID 31064392, 2019). "Notably, all BRCA1-deficient breast cancers with PTEN mutation clustered within the Thigh group whereas the sole BRCA2-deficient breast cancer with PTEN mutation clustered within the Tlow group." (PMID 31022191, 2019).
breast cancer (continued). "In agreement with a previous report that BRCA1 acts as a pivotal suppressor of EZH2 in the PRC2 complex 42, it has been shown recently that EZH2 represses expression of FOXO3, but this regulation only occurs when EZH2 becomes hyperactivated in BRCA1-deficient breast cancer cells." (PMID 31410199, 2019). "Our results indicate that co-occurring truncating variants might be associated with an earlier onset of breast cancer in BRCA1-positive patients." (PMID 31395037, 2019). "Additionally, a trial among women with high risk of breast cancer due to mutations to breast cancer type 1 (BRCA1) susceptibility gene showed increased risk of all cancers and primary breast cancer in Se-supplemented arm compared to placebo." (PMID 31252568, 2019). "Importantly, however, these analyses revealed that PALB2-associated breast cancers with bi-allelic inactivation differ from non-BRCA1/2/PALB2-associated breast cancers but are similar to BRCA1 and BRCA2 breast cancers with bi-allelic inactivation." (PMID 31428676, 2019). "The risk of developing breast cancer by age 80 in women carrying a BRCA1 pathogenic variant is 72%." (PMID 31395037, 2019). "In addition, BRCA1-mutated breast cancer shows predilection for posterior breast and prepectoral region and show fibroadenoma-like benign morphologic features such as oval/round shape and smooth margins, or non-mass-like enhancement on MRI." (PMID 31781977, 2019). "FANCA variants have been reported in non-BRCA1/2 familial breast cancer patients." (PMID 30709382, 2019). "BRCA1/2 pathogenic variants confer more than 50% risk of breast cancer development." (PMID 31658756, 2019). "To investigate whether BRRM leads to survival benefit, we determined the overall and breast cancer-specific mortality rates among 2857 healthy BRCA1/2 mutation carriers opting for either BRRM or surveillance with follow-up until 2017." (PMID 31302855, 2019). "How does the BRCA1 mutation disturb the salivary redox profile in breast cancer patients?" (PMID 31597313, 2019). "In agreement with this hypothesis, decreased SIRT1 levels have been observed in BRCA1-mutated breast cancers." (PMID 30939818, 2019). "In this study, 11 BRCA1 mutations were detected in Chinese patients with breast cancer." (PMID 30968603, 2019). "Moreover, revisiting whole-exome sequencing datasets of non-BRCA1/2 familial breast cancer patients confirmed the existence of likely pathogenic germline variants in MRE11A, RAD50, and NBN, encoding components of the MRN complex." (PMID 31921645, 2019). "The relatively low rate of mutations in the BRCA1 and 2 genes in this high-risk population with breast cancer diagnosed in the relatively young, suggests that mutations in other genes may be prevalent." (PMID 30675319, 2019). "Therefore we evaluated our data for the criteria for hereditary breast cancer with BRCA1 or BRCA2 mutations, Lynch syndrome/Lynch-mimic-syndrome and Li-Fraumeni syndrome." (PMID 30998723, 2019). "Among these mutations, two truncating mutations were found in 15 BRCA1/2-negative high-risk breast cancer families by whole-exome sequencing, and another two were found in 438 validating BRCA1/2-negative breast cancer families screened over the entire coding region by Sanger sequencing." (PMID 30967997, 2019). "Here we develop genetically engineered mouse models (GEMMs) of BRCA1-deficient breast cancer that permit rapid introduction of putative drivers by either retargeting of GEMM-derived embryonic stem cells, lentivirus-mediated somatic overexpression or in situ CRISPR/Cas9-mediated gene disruption." (PMID 30674894, 2019).
breast cancer (continued). "Women with a mutation in the BRCA1 face as high as 80% lifetime risk of developing breast cancer." (PMID 31518337, 2019). "However, BRCA1/2 variants distributions are vary among populations, statistics about hereditary breast cancer among the Arabs origin are very scarce." (PMID 31528229, 2019). "However, the TT genotype has been found associated with a poor prognosis previously, including in a breast cancer study in BRCA1/2 mutation carriers." (PMID 30691044, 2019). "We selected patients with familial breast cancer based on the BRCA1/2 mutation status." (PMID 31307407, 2019). "A proportion of breast cancers are attributable to BRCA1 or BRCA2 mutations." (PMID 30689103, 2019). "Indeed, germline pathogenic variants in the two major breast cancer susceptibility genes BRCA1/2 have been detected within Chinese patients." (PMID 31174498, 2019). "For BRCA1, the highest mutation frequency was noted in families with breast and ovarian cancer (53.8%), followed by families with at least three breast cancer cases (24.8%), families with two breast cancer cases (18.3%), or families with one early-onset breast cancer case (<30 years) (10.8%)." (PMID 31528241, 2019). "In addition, our findings suggest that the BRCA1 mutation can cause a predisposition to early salivary gland dysfunction, both in patients with breast cancer and in healthy individuals, leading to a decrease in the concentration of salivary proteins." (PMID 31597313, 2019). "BRCA1 is a DNA repair protein, best known for its association with breast cancer." (PMID 31655065, 2019). "As DNA methylation data is not available for this dataset, we tested whether DNA methylation is lower in BRCA1/2-mutated tumors in a cohort of 674 breast cancers and 97 normal breast tissue samples from The Cancer Genome Atlas." (PMID 31182087, 2019). "As part of the exploratory analysis, we investigated whether PALB2-associated breast cancers would differ from non-BRCA1/2/PALB2-associated breast cancers in regard to the frequencies of genomic features indicative of HRD." (PMID 31428676, 2019). "This new area of hormonal influence due to BRCA1 mutation may be associated with increasing risk for breast cancer." (PMID 31771627, 2019). "About 5–10% of all breast cancer is caused by germline variants in BRCA1/2." (PMID 31658756, 2019). "Women who inherit a BRCA1 or BRCA2 mutation have an increased risk of breast cancer." (PMID 31407530, 2019). "The BRCA1 mutation, in both healthy subjects and breast cancer patients, may predispose them to impaired secretory function of the salivary glands." (PMID 31597313, 2019). "Given that the function of any PSi-based biosensor ishighly dependent on its nanomorphology, we systematically optimized a PSi biosensor based on reflectometric interferencespectroscopy (RIS) detecting the high penetrance breast cancer susceptibility gene, BRCA1." (PMID 30124007, 2019). "BRCA1/2 mutations were identified in 24.7% of Pakistani breast cancer families." (PMID 31528241, 2019). "The first group consist of BRCA1/2-deficient breast cancers with T cell-inflamed signature score above the median (Thigh) while the second group consist of BRCA1/2-deficient breast cancers with T cell-inflamed signature score equal to or below the median (Tlow)." (PMID 31022191, 2019).